RHOV (ras homolog family member V)
Diseases named in the same sentence as RHOV in open-access papers (continued):
Sharing a sentence is not in itself a finding about the gene and the disease.
tumor (continued). "qRT-PCR and IHC showed increased ANLN, RHOV, and KRT6A expression in the LUAD cells and tumor tissues." (PMID 37974107, 2023). "ImageJ software calculated the positivity rate, and the results confirmed that ANLN, RHOV, and KRT6A were all significantly upregulated in the tumor samples." (PMID 37974107, 2023). "In order to identify the key regulators in the ICD risk subgroups, first we verified the mRNA expression levels of these eight genes, and we found that only SFTPB and SERPIND1 were highly expressed in normal tissues, whereas FAM83A, FDCSP, KRT6A, RHOV and TPX2 were highly expressed in tumor tissues." (PMID 39247599, 2024). "Furthermore, knockdown RhoV, by esiRNA or plasmids, was exhibited great inhibition of LUAD cell proliferation in vitro, meanwhile inhibited the formation of tumor growth in vivo." (PMID 33767988, 2021). "RHOV expression was relatively low in ACC samples, with no differential expression between tumor and normal tissues." (PMID 37596964, 2023). "In KIRC, the GSE36895 dataset showed downregulated expression of RHOV in tumors compared with normal tissues, which was consistent with the results from TCGA_GTEx, whereas the GSE53757 dataset showed no differential expression between matched tumor and normal tissues." (PMID 37596964, 2023).
cancer (6 papers, 2017 to 2024). A tumor composed of atypical neoplastic, often pleomorphic cells that invade other tissues. "In this comprehensive study, the expression and prognostic role of RHOV in pan‐cancer were thoroughly investigated." (PMID 37596964, 2023). "In conclusion, our study revealed the dysregulation of RHOV expression in various tumors and identified its prognostic significance in several cancer types." (PMID 37596964, 2023). "In this study, we investigated the expression of RHOV in pan‐cancer analysis using The Cancer Genome Atlas (TCGA) and Gene‐Tissue Expression datasets." (PMID 37596964, 2023). "This analysis can provide further insight into the potential biological functions of RHOV as a candidate target for new pan‐cancer immunotherapies and treatment strategies." (PMID 37596964, 2023). "Our study used in silica data mining to explore the prognostic and immunological roles of RHOV in various cancer types." (PMID 37596964, 2023). "Regarding RhoV function in cancer cells, RhoV has been verified that alters cell shape and cell adhesion." (PMID 33767988, 2021). "Top‐100 genes of most similar expression pattern with RHOV in pan‐cancer." (PMID 37596964, 2023). "However, further experimental investigations are required to validate the functional roles of RHOV in specific cancer types and its impact on TIICs and patient survival." (PMID 37596964, 2023). "Therefore, in this study, we performed a comprehensive bioinformatic analysis to investigate the prognostic significance of RHOV expression in pan‐cancer." (PMID 37596964, 2023). "Univariate Cox regression of RHOV expression with OS in pan‐cancer." (PMID 37596964, 2023). "Third, the exact mechanism by which RHOV affects the survival of patients with cancer through the regulation of TIICs remains unknown." (PMID 37596964, 2023). "Whether RHOV regulates cancer cell growth and metastasis through other signaling pathways remains to be investigated." (PMID 34326698, 2021). "Additionally, RHOV expression correlated with the distribution of different TIICs in these cancers." (PMID 37596964, 2023). "No point mutations related to cancer have been reported for RHOU or RHOV to date." (PMID 35454871, 2022). "However, the biological function of RHOV in human cancer is unclear." (PMID 34326698, 2021). "RHOV silencing inhibited proliferation and migration, as well as improved the sensitivity of EGFR-TKI and increased cancer cell apoptosis in gefitinib-resistant PC9 cells." (PMID 39478862, 2024). "Previous studies demonstrated that RHOV functions as an oncogene in LUAD, promoting cancer cell growth, metastasis, and resistance to epidermal growth factor receptor (EGFR)‐tyrosine kinase inhibitor therapies." (PMID 37596964, 2023). "However, whether RHOV stimulates JNK pathway in human cancer cells is unknown." (PMID 34326698, 2021). "Additionally, RHOV activates EGFR signaling through GRB2, thereby regulating cancer cell migration and promoting metastasis in TNBC." (PMID 37596964, 2023). "Importantly, we revealed for the first time that RHOV promotes growth, EMT and metastasis through JNK phosphorylation in human cancer." (PMID 34326698, 2021).
infection (1 paper, 2021). The state of being infected such as from the introduction of a foreign agent such as serum, vaccine, antigenic substance or organism. "We found that RhoV promotes infection of some flaviviruses and acts at the step of viral entry." (PMID 34834920, 2021). "We then asked whether RhoV has an effect on infection of other positive-sense single-stranded RNA viruses." (PMID 34834920, 2021).
RHOV also shares sentences with these, for which no sentence is quoted: adenoid cystic carcinoma (1 paper); Alzheimer disease (1); bladder urothelial carcinoma (1); breast carcinoma (1); breast invasive carcinoma (1); carcinoid (1); cervical cancer (1); cervical squamous cell carcinoma (1); cholangiocarcinoma (1); colon adenocarcinoma (1); diffuse large B-cell lymphoma (1); endocervical adenocarcinoma (1); endometrial cancer (1); esophageal carcinoma (1); glioblastoma multiforme (1); glioma (1); head and neck cancer (1); kidney chromophobe (1); leukemia (1); lung squamous cell carcinoma (1); lymphoma (1); non-small cell lung carcinoma (1); ovarian serous cystadenocarcinoma (1); pancreatic cancer (1); pancreatic ductal adenocarcinoma (1); prostate adenocarcinoma (1); rectum adenocarcinoma (1); renal carcinoma (1); skin cancer (1); skin cutaneous melanoma (1).
A further 9 diseases each share a sentence with RHOV in 1 paper.